MAJIN (membrane anchored junction protein)
Description:
Meiosis-specific telomere-associated protein involved in meiotic telomere attachment to the nucleus inner membrane, a crucial step for homologous pairing and synapsis. Component of the MAJIN-TERB1-TERB2 complex, which promotes telomere cap exchange by mediating attachment of telomeric DNA to the inner nuclear membrane and replacement of the protective cap of telomeric chromosomes: in early meiosis, the MAJIN-TERB1-TERB2 complex associates with telomeric DNA and the shelterin/telosome complex. During prophase, the complex matures and promotes release of the shelterin/telosome complex from telomeric DNA. In the complex, MAJIN acts as the anchoring subunit to the nucleus inner membrane. MAJIN shows DNA-binding activity, possibly for the stabilization of telomere attachment on the nucleus inner membrane.
Synonyms: C11orf85
Tractability: Antibody: UniProt predicts a signal peptide or a membrane-spanning region.
Gene: Protein-coding gene on chromosome 11 (64,937,517 to 64,972,108, reverse strand). Ensembl gene ENSG00000168070.
Subcellular location: Nucleus inner membrane; Chromosome, telomere
Gene Ontology:
Molecular function: protein binding; DNA binding
Biological process: protein localization to nuclear envelope; homologous chromosome pairing at meiosis; meiotic attachment of telomere to nuclear envelope; meiotic telomere clustering
Cellular component: nuclear membrane; chromosome, telomeric region; nuclear inner membrane; nuclear envelope
Genetic constraint (gnomAD): Loss-of-function variants: 27 observed, 29.71 expected, observed/expected ratio (o/e) 0.91, 90% interval 0.67 to 1.25. The upper end of that interval is the gene's LOEUF score, 1.25, which puts it in group 5 of 6, group 1 being the genes least tolerant of losing a copy. Missense variants: 253 observed, 268.48 expected, observed/expected ratio (o/e) 0.94, 90% interval 0.85 to 1.05. Synonymous variants: 78 observed, 96.68 expected, observed/expected ratio (o/e) 0.81, 90% interval 0.67 to 0.97.
Homologues: Orthologues: chimpanzee MAJIN (99% identical), macaque MAJIN (96% identical), mouse Majin (62% identical), rat Majin (62% identical), guinea pig MAJIN (60% identical), rabbit MAJIN (50% identical), tropical clawed frog majin (29% identical), zebrafish MAJIN (27% identical).
Diseases named in the same sentence as MAJIN in open-access papers:
MAJIN is named in the same sentence as 2 diseases in open-access papers, as found by Europe PMC text mining. Sharing a sentence is not in itself a finding about the gene and the disease. The quoted sentences say what the papers report.
Infertility (3 papers, 2019 to 2024). "In humans, biallelic mutations in MAJIN have been reported in infertile males and those in KASH5 and TERB1 in infertile males and in females with POI." (PMID 39545410, 2024). "Likewise, mice disrupted for either MAJIN or TERB2 display impaired synapsis, zygotene arrest, a lack of post-meiotic cells, and infertility phenotype as revealed by Salas-Huetos." (PMID 35342767, 2022).
male infertility (1 paper, 2022). The inability of the male to effect fertilization of an ovum after a specified period of unprotected intercourse. "Furthermore, disruption or mutations of any of the MTC genes (TERB1, TERB2, and MAJIN) alters telomere association with the nuclear envelope leading to impairment of homologous pairing and synapsis, a meiotic arrest, and consequently to male infertility." (PMID 35342767, 2022). "The main goal of this work was exploring the effects of missense mutations on meiotic telomere complex proteins (TERB1, TERB2, and MAJIN) related to male infertility." (PMID 35342767, 2022).